FOXO3 (forkhead box O3)
Description:
Transcriptional activator that recognizes and binds to the DNA sequence 5'-[AG]TAAA[TC]A-3' and regulates different processes, such as apoptosis and autophagy. Acts as a positive regulator of autophagy in skeletal muscle: in starved cells, enters the nucleus following dephosphorylation and binds the promoters of autophagy genes, such as GABARAP1L, MAP1LC3B and ATG12, thereby activating their expression, resulting in proteolysis of skeletal muscle proteins (By similarity). Triggers apoptosis in the absence of survival factors, including neuronal cell death upon oxidative stress. Participates in post-transcriptional regulation of MYC: following phosphorylation by MAPKAPK5, promotes induction of miR-34b and miR-34c expression, 2 post-transcriptional regulators of MYC that bind to the 3'UTR of MYC transcript and prevent its translation. In response to metabolic stress, translocates into the mitochondria where it promotes mtDNA transcription. In response to metabolic stress, translocates into the mitochondria where it promotes mtDNA transcription. Also acts as a key regulator of chondrogenic commitment of skeletal progenitor cells in response to lipid availability: when lipids levels are low, translocates to the nucleus and promotes expression of SOX9, which induces chondrogenic commitment and suppresses fatty acid oxidation (By similarity). Also acts as a key regulator of regulatory T-cells (Treg) differentiation by activating expression of FOXP3.
Synonyms: FKHRL1; FOXO3A; AF6q21; FOXO2; FKHRL1P2
Tractability: Small molecule: a structure with a bound ligand is known. Antibody: UniProt places it where antibodies can reach, with high confidence. PROTAC: UniProt records ubiquitination sites on it; ubiquitination databases record sites on it.
Target class: Transcription factor
Gene: Protein-coding gene on chromosome 6 (108,559,652 to 108,684,774, forward strand). Ensembl gene ENSG00000118689.
Subcellular location: Cytoplasm, cytosol; Nucleus; Mitochondrion matrix; Mitochondrion outer membrane
Subcellular location (Human Protein Atlas): Nucleoplasm
Pathways (Reactome):
Gene expression (Transcription): FOXO-mediated transcription of cell cycle genes; FOXO-mediated transcription of cell death genes; FOXO-mediated transcription of oxidative stress, metabolic and neuronal genes; RUNX3 regulates BCL2L11 (BIM) transcription; Regulation of FOXO transcriptional activity by acetylation; Regulation of localization of FOXO transcription factors
Signal Transduction: AKT phosphorylates targets in the nucleus; Estrogen-dependent nuclear events downstream of ESR-membrane signaling; MAPK6/MAPK4 signaling
Disease: Constitutive Signaling by AKT1 E17K in Cancer; Deregulated CDK5 triggers multiple neurodegenerative pathways in Alzheimer's disease models
Immune System: FLT3 Signaling; Interleukin-4 and Interleukin-13 signaling
Cellular responses to stimuli: Mitochondrial unfolded protein response (UPRmt)
Developmental Biology: Signaling by NODAL
Gene Ontology:
Molecular function: beta-catenin binding; DNA binding; DNA-binding transcription activator activity, RNA polymerase II-specific; DNA-binding transcription factor activity; DNA-binding transcription repressor activity, RNA polymerase II-specific; mitochondrial transcription factor activity; protein binding; protein kinase binding; sequence-specific DNA binding; sequence-specific double-stranded DNA binding; chromatin DNA binding; DNA-binding transcription factor activity, RNA polymerase II-specific; RNA polymerase II cis-regulatory region sequence-specific DNA binding; transcription cis-regulatory region binding; transcription coregulator binding
Biological process: cellular response to glucose starvation; mitochondrial transcription; negative regulation of cell migration; negative regulation of transcription by RNA polymerase II; positive regulation of apoptotic process; positive regulation of DNA-templated transcription; positive regulation of erythrocyte differentiation; positive regulation of neuron apoptotic process; positive regulation of regulatory T cell differentiation; positive regulation of transcription by RNA polymerase II; regulation of translation; tumor necrosis factor-mediated signaling pathway; cellular response to oxidative stress; positive regulation of autophagy; positive regulation of miRNA transcription; positive regulation of muscle atrophy; regulation of transcription by RNA polymerase II; response to fatty acid; response to starvation; cellular response to amyloid-beta; cellular response to corticosterone stimulus; cellular response to glucose stimulus; cellular response to nerve growth factor stimulus; negative regulation of neuron differentiation; positive regulation of hydrogen peroxide-mediated programmed cell death; and 5 more
Cellular component: cytoplasm; cytosol; mitochondrial matrix; mitochondrial outer membrane; mitochondrion; nucleoplasm; nucleus; protein-containing complex; RNA polymerase II transcription repressor complex; chromatin; membrane
Genetic constraint (gnomAD): Loss-of-function variants: 3 observed, 29.83 expected, observed/expected ratio (o/e) 0.1, 90% interval 0.045 to 0.26. The upper end of that interval is the gene's LOEUF score, 0.26, which puts it in group 1 of 6, group 1 being the genes least tolerant of losing a copy. Missense variants: 470 observed, 662.33 expected, observed/expected ratio (o/e) 0.71, 90% interval 0.66 to 0.77. Synonymous variants: 287 observed, 287.48 expected, observed/expected ratio (o/e) 1, 90% interval 0.91 to 1.1.
Homologues: Orthologues: chimpanzee FOXO3 (99% identical), macaque FOXO3 (99% identical), pig FOXO3 (96% identical), dog FOXO3 (96% identical), mouse Foxo3 (95% identical), rabbit FOXO3 (95% identical), rat Foxo3 (95% identical), guinea pig FOXO3 (91% identical), tropical clawed frog foxo3 (71% identical). Paralogues in human: FOXO1 (43% identical), FOXO4 (33% identical), FOXO6 (32% identical), FOXM1 (14% identical), FOXJ3 (12% identical), FOXJ2 (12% identical), FOXC1 (11% identical), FOXK2 (11% identical), FOXD4 (11% identical), FOXD4L1 (11% identical), FOXN1 (11% identical), FOXA2 (11% identical), and 29 more.
Diseases named in the same sentence as FOXO3 in open-access papers:
FOXO3 is named in the same sentence as 417 diseases in open-access papers, as found by Europe PMC text mining. Sharing a sentence is not in itself a finding about the gene and the disease. The quoted sentences say what the papers report.
breast carcinoma (380 papers, 2008 to 2025). "PI3K, AKT, and dual PI3K/mTOR inhibitors enhance FOXO3 nuclear localisation in breast cancer cells which is implicated in both sensitivity and feedback mediated resistance to pathway inhibition." (PMID 40263319, 2025). "Circ-Foxo3 has been linked to the growth and carcinogenesis of a number of malignancies, including breast cancer, according to earlier research." (PMID 37400900, 2023). "FOXA1 is a central regulator of gene expression programs in ER+ breast cancer, FOXC1 is associated with EMT and poor prognosis in basal-like breast cancer, and FOXO3 is often dysregulated and plays both tumor-suppressive and oncogenic roles." (PMID 37234983, 2023). "Their concluded that FOXO3 down regulation and miR-182 upregulation are associated with advanced breast cancer." (PMID 36681070, 2023). "Further, the tumour-suppressive role of FOXO3 is studied in various human cancers, and its nuclear localization is linked with a better prognosis in breast cancer." (PMID 36727057, 2022). "A classical tumor suppressive role of FOXO3 in a very small subset of breast cancers is further supported by recurrent mutations (n = 38, 1.4%), almost half of them being associated with deletions of the second allele." (PMID 34625909, 2022). "Overall, our data provide some insight into the clinical importance of the FOXO3 gene, and further investigation will aid in developing effective pharmacological approach in targeting FOXO3 and its associated pathway in breast cancer cases." (PMID 36727057, 2022). "Correlation study of methylation and protein expression in samples having methylated FOXO3 promoter or FOXO3 expression loss with clinical parameters of Breast cancer patients from North Indian population." (PMID 36727057, 2022). "When investigated, it was found that the promoter methylation of FOXO3 substantially linked with the histological grade and lymph node status of breast cancer (p=0.01 and p=0.003)." (PMID 36727057, 2022). "Reduced expression of FoxO1 and FoxO3 is associated with resistance to conventional agents and with reduced efficacy of drug combinations in ovarian and breast cancer cells." (PMID 31906031, 2019). "Here, we provide evidence for the association between LINC01355 and FOXO3 protein in breast cancer cells." (PMID 31243265, 2019). "RNA and protein analysis of a panel of breast cancer cell lines revealed that BRCA1 deficiency is associated with downregulation of the expression of the pleiotropic tumour suppressor FOXO3." (PMID 27043660, 2016). "Together, these data support the idea that EZH2 negatively regulates FOXO3 transcription in BRCA1-deficient breast cancer cells, whereas this EZH2 activity is repressed by BRCA1 in BRCA1-competent cells." (PMID 27043660, 2016). "Circ-Foxo3, as a circular RNA, has been linked to the breast cancer lethal traits." (PMID 37400900, 2023). "In breast cancer, FOXO3 overexpression was shown to be associated with tumor suppression." (PMID 38202222, 2023). "Moreover, the result is congruous with earlier observations that linked the downregulation of FOXO3 with the advancement of renal cell carcinoma, gastric cancer, and breast cancer." (PMID 36727057, 2022). "ER and FOXO3 are intimately and paradoxically linked in breast cancer." (PMID 31439835, 2019). "Consistent with this, immunohistochemistry results from different breast cancer subtypes showed that high SIRT6/1 levels are associated with constitutive high FOXO3 expression which is related to FOXO3 deregulation/inactivation and poor prognosis in breast cancer patient samples." (PMID 31357743, 2019). "Furthermore, immunohistochemistry further suggested that FOXO3 expression was significantly associated with BRCA1 status in EZH2-positive breast cancer." (PMID 27043660, 2016).
breast carcinoma (continued). "To further affirm our results, we also investigated the correlation between BRCA1 mutation status and FOXO3 protein expression levels in human samples by immunohistochemical staining on tissue microarray constructed from 308 Korean breast cancer cases with known BRCA1 status." (PMID 27043660, 2016). "Consequently, loss of function of FOXO3 has been linked to tumorigenesis and poor patient survival in breast cancer and other cancers such as lung cancer, prostate cancer, and ovarian cancer." (PMID 27283899, 2016). "Among the four FoxO family members, FoxO3 is the isoform that has been associated with human longevity, breast cancer suppression in humans, and in the maintenance of adult hematopoietic and neural stem cells, a potentially important process in maintaining health late in life." (PMID 22820736, 2012). "In our current study, we found that in breast cancer cells, overexpression of FOXO3 also downregulated the expression of SOX2." (PMID 39991565, 2025). "In conclusion, increased FOXO3 and decreased E-cadherin in breast cancer cells can induce anoikis through direct activation of BMF." (PMID 40003882, 2025). "As Dicer is an RNase that suppresses metastasis, geminin facilitates breast cancer cell metastasis via the geminin/HDAC3/FOXO3/Dicer pathway." (PMID 40003882, 2025). "Consistently, the results of UALCAN database analysis corroborated reduced FOXO3 protein levels in breast cancer tissues." (PMID 40589632, 2025). "FOXO3 is commonly known as a tumor suppressor, and its expression level and activity are negatively related to the malignancy of breast cancer." (PMID 40003882, 2025). "The downregulation of the FOXO3 gene and the subsequent decrease in FOXO3 protein levels are commonly observed in breast cancer cells." (PMID 40003882, 2025). "FOXO3 has been identified as a suppressor of breast cancer, as it can inhibit tumor progression and suppress BCSC properties." (PMID 40003882, 2025). "Reduction of FOXO3 or overexpression of CCND1 can reverse the inhibitory action posed by LINC01355 on proliferation of breast cancer cells In TNBC another tumor suppressor lncRNA (SONE) has been investigated." (PMID 39912983, 2025). "To summarize, the silencing of both EZH2 and NIR can boost the expression of FOXO3 and suppress breast cancer cell proliferation." (PMID 40003882, 2025). "The promotion of BC cell migration by F. nucleatum infection can be attributed to the enhancement of breast cancer cell EMT through the miR-21-3p/FOXO3 axis." (PMID 40589632, 2025). "To investigate the effect of propofol and FOXO3 on breast cancer cell stemness, we analyzed the percentage of ESA+/CD44+/CD24-/low cells by flow cytometry." (PMID 39991565, 2025). "Herein, we investigated the role of propofol and explored the mechanism of propofol-FOXO3 in BCSCs and breast cancer proliferation." (PMID 39991565, 2025). "In our present study, we found that the stemness of breast cancer cells was significantly inhibited by overexpressed FOXO3 after propofol treatment." (PMID 39991565, 2025). "For instance, FOXF2 and FOXO3 both function as tumor suppressors in HER2-positive breast cancer and have limited expression levels." (PMID 40003882, 2025). "FOXO3 (Forkhead Box O3) was identified to be up regulated in 24h propofol treatment breast cancer cells." (PMID 39991565, 2025). "Through the use of western blot analysis, we found that, compared with those in control cells, the protein levels of FoxO3 and phospho-FoxO3 in MCF-7 or MDA-MB-231 breast cancer cells were dramatically lower in the JNKi-treated cells." (PMID 39420837, 2024). "High expression of FOXO3 has a favorable prognosis in acute myeloid leukemia 289, breast cancer 290, bladder cancer 291, gastric cancer 292, nasopharyngeal carcinoma 293 and human ovarian cancer." (PMID 38725864, 2024).
breast carcinoma (continued). "RHBDF1 deficiency leads to decreased JNK-mediated FoxO3 translocation into the cell nucleus, resulting in a reduction in PERK and its downstream proteins pPERK and peIF2α in breast cancer cells." (PMID 39420837, 2024). "By using immunofluorescence staining, we also demonstrated a decrease in FoxO3 and phospho-FoxO3 inRHBDF1-knockout MCF-7 andRHBDF1-silenced MDA-MB-231 breast cancer cells." (PMID 39420837, 2024). "In the present study, we demonstrated that RHBDF1 is able to facilitate PERK expression through the Forkhead box O3 (FoxO3) transcription factor in breast cancer cells." (PMID 39420837, 2024). "The anti-cancer effect of vernodalin was mediated by FOXO3 in breast cancer cells in vitro and breast tumor growth in vivo." (PMID 39334758, 2024). "It has been shown to selectively couple transcription factor forkhead box O3 to histone deacetylase and block its activity, ultimately downregulating its target Dicer, an RNase that suppresses metastasis in breast cancer." (PMID 38659554, 2024). "We investigated the involvement of RHBDF1 in FoxO3 translocation in breast cancer cells to better understand the mechanism by which RHBDF1 controls FoxO3 transcriptional activity." (PMID 39420837, 2024). "Anagallis arvensis extract exhibited anti-cancer and radio-sensitizing effects on breast cancer cells by upregulating the expression of FOXO3." (PMID 39334758, 2024). "It has been reported that Gly exposure induced proliferation of breast cancer cells through upregulation of FOXO3 mRNA expression." (PMID 38297317, 2024). "Fagonia cretica (recently corrected as Fagonia indica) extract induced cell cycle arrest and apoptosis in MCF7 and MDA-MB-231 breast cancer cells through the expression of FOXO3." (PMID 39334758, 2024). "Delphinidin triggered apoptosis and autophagy in HER-2-positive breast cancer cells by activating the AMPK/FOXO3 pathway." (PMID 39334758, 2024). "In the current work, we found that multicellular breast cancer spheroids have significantly less circ-Foxo3 expression." (PMID 37400900, 2023). "We argued that by down regulating circ-Foxo3, breast CSCs can evade apoptosis because of the crucial role that circ-Foxo3 plays in the apoptosis of breast cancer cells." (PMID 37400900, 2023). "They demonstrated that circ-Foxo3 was weakly expressed in both patient tumor samples (relative to benign tissue) and a panel of breast cancer cell lines (compared to normal cell lines)." (PMID 37400900, 2023). "Oxidative stress activates the transcription factor forkhead box O3 (FOXO3) in MCF-7 breast cancer cells, increasing the transcription of autophagy-related LC3 and BNIP3." (PMID 36829987, 2023). "For instance, FOXO3 activation promotes apoptosis in many cell lines, including those for breast cancer, oral squamous cell carcinoma, osteosarcoma, gastric cancer, and ovarian cancer." (PMID 37174744, 2023). "Our results indicate that Circ-Foxo3 expression has been grossly altered in these multicellular spheroids that contain breast cancer stem-like cells." (PMID 37400900, 2023). "Activated PI3K/AKT downregulates forkhead box O3 (FOXO3a) expression levels and enhances breast cancer stemness and therapeutic resistance." (PMID 36632469, 2023). "Compared with breast tumor cells in 2D monolayer, circ-Foxo3 was downregulated 2.3 time in multicellular breast cancer spheroids." (PMID 37400900, 2023). "Another study verified dephosphorylated FOXO3 (active FOXO3) to suppress breast cancer growth and favor apoptosis in a rat model in vivo." (PMID 38132107, 2023). "In breast cancer cell lines, active FOXO3 has been reported to displace FOXM1 from the VEGF promoter, thereby reducing VEGF gene expression." (PMID 37174744, 2023). "Conversely, LINC01355 inhibits the growth of breast cancer by inhibiting FOXO3-mediated CCND1 transcription." (PMID 35664432, 2022).